ITGAE (integrin subunit alpha E)
Description:
Integrin ITGAE/ITGB7 (alpha-E/beta-7) is a receptor for E-cadherin. It mediates adhesion of intra-epithelial T-lymphocytes to epithelial cell monolayers.
Synonyms: CD103; HUMINAE
Tractability: Antibody: its Gene Ontology location is reachable by antibodies, with high confidence; UniProt predicts a signal peptide or a membrane-spanning region.
Gene: Protein-coding gene on chromosome 17 (3,714,628 to 3,801,193, reverse strand). Ensembl gene ENSG00000083457.
Subcellular location: Membrane
Pathways (Reactome):
Extracellular matrix organization: Integrin cell surface interactions
Gene Ontology:
Molecular function: signaling receptor activity
Biological process: cell-cell adhesion; cell-matrix adhesion; integrin-mediated signaling pathway; cell adhesion
Cellular component: integrin alphaE-beta7 complex; cell surface; integrin complex; plasma membrane; external side of plasma membrane; membrane
Genetic constraint (gnomAD): Loss-of-function variants: 85 observed, 107.57 expected, observed/expected ratio (o/e) 0.79, 90% interval 0.66 to 0.95. The upper end of that interval is the gene's LOEUF score, 0.95, which puts it in group 4 of 6, group 1 being the genes least tolerant of losing a copy. Missense variants: 1,248 observed, 1,348.7 expected, observed/expected ratio (o/e) 0.93, 90% interval 0.88 to 0.97. Synonymous variants: 542 observed, 529.78 expected, observed/expected ratio (o/e) 1.02, 90% interval 0.95 to 1.1.
Homologues: Orthologues: chimpanzee ITGAE (99% identical), macaque ITGAE (92% identical), pig ITGAE (75% identical), dog ITGAE (74% identical), guinea pig ITGAE (74% identical), rabbit ITGAE (72% identical), rat Itgae (70% identical), mouse Itgae (69% identical), tropical clawed frog itgae (37% identical), zebrafish itgae.2 (28% identical), Drosophila melanogaster mew (18% identical), Caenorhabditis elegans ina-1 (16% identical), and 6 more. Paralogues in human: ITGAM (28% identical), ITGAD (28% identical), ITGAX (27% identical), ITGA1 (24% identical), ITGAL (24% identical), ITGA10 (23% identical), ITGA11 (23% identical), ITGA2 (23% identical), ITGA4 (18% identical), ITGA9 (18% identical), ITGAV (18% identical), ITGA5 (17% identical), and 5 more.
Diseases named in the same sentence as ITGAE in open-access papers:
ITGAE is named in the same sentence as 267 diseases in open-access papers, as found by Europe PMC text mining. Sharing a sentence is not in itself a finding about the gene and the disease. The quoted sentences say what the papers report.
melanoma (100 papers, 2016 to 2026). A malignant, usually aggressive tumor composed of atypical, neoplastic melanocytes. "In melanoma, IL-15 expression positively correlates with TRM abundance and higher mRNA levels of ITGAE (CD103), ITGA1 (CD49a), and CD69, reinforcing its role in maintaining residency and effector potential." (PMID 41479900, 2025).
lung carcinoma (45 papers, 2016 to 2025). "CD103+ TRM, both in tumor and non-tumor tissue, are marked by expression of PDCD1, ITGAE, CXCR6, and SPRY1 in lung cancer." (PMID 32471032, 2020).
breast carcinoma (37 papers, 2015 to 2026). "Using a Cox proportional hazards model, higher ITGAE expression was also significantly associated with poorer survival in adrenocortical carcinoma as well as in primary cutaneous melanoma, breast carcinoma, kidney renal cell carcinoma and kidney chromophobe cancer." (PMID 33479027, 2021). "Analysis of TCGA data demonstrated that high expression of ITGAE (encoding CD103) was associated with reduced survival in primary cutaneous melanoma, breast carcinoma, renal cell carcinoma, kidney chromophobe cancer, adrenocortical carcinoma and lower grade glioma." (PMID 33479027, 2021).
psoriasis (34 papers, 2005 to 2025). An autoimmune condition characterized by red, well-delineated plaques with silvery scales that are usually on the extensor surfaces and scalp. "Strikingly, the majority of IL26+ T cells in both nonlesional and lesional skin of psoriasis patients as well as in healthy skin expressed the TRM marker CD103 (ITGAE), indicating that IL26+ TH17 intermediates in the skin derive from skin-resident rather than circulating T cells." (PMID 37391412, 2023).
ovarian carcinoma (23 papers, 2018 to 2025). A malignant neoplasm originating from the surface ovarian epithelium. "Published data highlighted that the abundance of ITGAE expression and CD8, correlates with a poor prognosis in cutaneous squamous carcinoma and clear cell renal cell carcinoma, while in contrast, the same abundance correlates with a better prognosis in colorectal and ovarian cancer." (PMID 36289717, 2022).
colorectal cancer (16 papers, 2019 to 2025). A primary or metastatic malignant neoplasm that affects the colon or rectum. "Concurrent analysis of TCGA datasets further associated high ITGAE (CD103) mRNA expression with poor survival in glioblastoma and colorectal cancer, although functional studies specifically addressing CD103+ TRM in colorectal cancer are still lacking." (PMID 41361844, 2025).
glioblastoma (9 papers, 2020 to 2025). The most malignant astrocytic tumor (WHO grade IV). "Additionally, our scRNA-seq dataset revealed FOXP3 expression in a small proportion of glioblastoma Tregs, and expression of ITGA1, ITGAE, and CXCR6 which are associated with a Trm signature." (PMID 35464424, 2022). "The significant negative correlation between ITGAE (encoding CD103) and CD69 gene expression and molecular markers of glioblastoma suggests that CD8+Trm cells may have an anti-tumor effect, as demonstrated by studies in other tumors." (PMID 36969190, 2023).
lung adenocarcinoma (8 papers, 2017 to 2025). A carcinoma that arises from the lung and is characterized by the presence of malignant glandular epithelial cells. "To confirm our data, we interrogated the TCGA data sets for HNSCC, lung adenocarcinoma, and lung squamous cell carcinoma, comparing patients with high expression of ENTPD1 (CD39) and ITGAE (CD103) transcripts to patients with lower expression of those genes." (PMID 30006565, 2018).
HIV-1 infection (3 papers, 2016 to 2025). The type species of lentivirus and the etiologic agent of acquired immunodeficiency syndrome (AIDS). "Both CD4+ and CD8+ T-cells expressing CD103/ItgαE and CD69 are affected during HIV-1 infection." (PMID 41227377, 2025).
meningioma (1 paper, 2022). A generally slow growing tumor attached to the dura mater. "We interrogated the TCGA database to determine whether ITGAE (CD103) and CD69, the two genes associated with CD8+ TRM T cells, were differentially expressed between GBM and meningioma patients." (PMID 36289717, 2022).
viral myocarditis (1 paper, 2022). Myocarditis that is caused by an infection with a viral agent. "The proteins ICAM1 (M3WBF1_FELCA) and CDH17 (M3WMR7_FELCA) were upregulated, while ITGAL (M3 WC52_FELCA) and ITGAE (M3W8N0_FELCA) were downregulated in the viral myocarditis pathway." (PMID 36290246, 2022).
tumor (832 papers, 2005 to 2026). "Cycling cells were predominantly T cells and mostly expressed the tissue residency marker CD103 (ITGAE) together with CD39 (ENTPD1) which has been associated with tumor specificity." (PMID 36253784, 2022). "Also, a gene expression signature obtained from tumor biopsies containing the gene (ITGAE) encoding for CD103 among other TIL-related genes (CD8A, CD8B, ITGAE [CD103], PDCD1 [PD-1], CCL5, CXCL13, and IL2) was associated with better outcomes to anti-PD1 therapy." (PMID 38562921, 2024). "These cells represented a relatively small proportion of the total T cell pool, and showed expression of ITGAE (encoding CD103), CXCL13, ENTDP1, PDCD1 and other checkpoint molecules consistent with previous antigen exposure and tumour reactivity." (PMID 41115454, 2025). "This was also accompanied by the upregulation of proliferation marker MKI67, costimulatory genes (CD28, TNFRSF9 (4-1BB), and tumor-reactivity markers (e.g., ENTPD1/CD39, ITGAE/CD103) suggestive of an anti-tumor response in face of rising tumor levels." (PMID 37919606, 2024). "Based on previous studies and the observation of local TCR clone expansion, the expression of ITGAE/ENTPD1 was considered to serve as a general marker for tumor‐reactiveness also for these CD4+/CD8+ T cells." (PMID 38582099, 2024). "As such, GEPIA2 was used to perform survival analysis of the TCGA-PAAD tumor dataset based on the expression of ITGAE, the gene encoding CD103." (PMID 36689623, 2023). "CD8-C1 highly expressed ZNF683 and ITGAE, represented a subpopulation of tissue-resident memory T cells (TRMs), which was reported as a considerable origin of tumor neoantigen specific T cells." (PMID 36138435, 2022). "Further validation of CD103 as a biomarker was provided through stratification of NSCLC patients in The Cancer Genome Atlas (TCGA) database, which showed that patients with high tumor ITGAE (CD103) expression have improved overall survival." (PMID 30555481, 2018). "We also identified other genes with well-established functions in T cells exhibiting novel differentially spliced isoforms along these lineages, including the tumor-reactive T-cell marker integrin subunit alpha E (ITGAE) and the proinflammatory cytokine high mobility group box 1 (HMGB1)." (PMID 41273175, 2025). "ITGAE is associated with a group of genes that have a cytotoxic function in CD8 cytotoxic T cells (CTSW, GNLY, NKG7, PRF1, GZMB, KLRK1) up-regulated in the tumor, identifying resident CD8 T cells in the tumor to have a highly cytotoxic and activated phenotype." (PMID 39548591, 2024). "Further, upregulated expression of CD39 (ENTPD1) was detected, a marker of persistent TCR stimulation on exhaustive T cells, co-expression of which with tissue-resident memory T cell marker CD103 (ITGAE) has been identified on tumor-reactive CD8-positive T cells in human solid cancers." (PMID 36341460, 2022). "Additionally, ccRCC patients with high intratumoral ITGAE (CD103) expression were found to have significantly shorter overall survival than patients with low ITGAE (CD103) expression within the tumor." (PMID 35326691, 2022). "Indeed, TGF-β is directly involved in CD103 expression in tumor-specific T cells upon engagement of TCR with specific tumor peptide–MHC-I complexes, through binding of Smad2/3 and NFAT-1 transcription factors to promoter and enhancer elements of the ITGAE gene, which encodes the CD103 (αE) subunit." (PMID 30158938, 2018). "Their proliferating CD4+ counterparts upregulated ENTPD1 (CD39) and ITGAE (CD103), like proliferating CD8+ T cells, and hence this mobilized population is enriched for putative tumor antigen specificity." (PMID 40299576, 2025). "Clonal expansion, representing the generation of tumor‐reactive T cells, suggests that CXCL13 and ITGAE are potential markers for tumor‐reactive T cells in MIBC." (PMID 39739621, 2025).
tumor (continued). "The 20 tumor samples were divided into high and low CD103 expression groups according to the median normalized count of ITGAE (coding CD103 protein)." (PMID 38183111, 2024). "ITGAE + TRM play an important role in immune surveillance and the restriction of tumor growth of solid tumors." (PMID 36982415, 2023). "We also noted that the tissue-resident marker ITGAE (CD103) was highly expressed in CD8+ T cells in the NAC group, indicating the presence of more tissue-resident CD8+ T cells in NAC tumor lesions." (PMID 37231145, 2023). "Results of data mining transcriptomes and clinical files from a large cohort of GBM samples revealed that the cumulative survival was higher in GBM patients with a high number of tumor-infiltrating CD8+ T cells and ITGAE (CD103) and CD69 positive cells." (PMID 36289717, 2022). "Similar to B-ALL, we also found that this population of T cells highly expressing ITGAE and MKI67 was elevated in the tumor microenvironment of multiple solid tumors." (PMID 36532049, 2022). "Most of TEX cells were likely tumor-reactive T cells because of high levels of CD39 (ENTPD1) and CD103 (ITGAE) and very low level of KLRG1 38–41." (PMID 34489433, 2021). "Conversely, we found GAD_CD14 derived signature being positively correlated with the expression of ITGAE (CD103) and TNFRSF9 (CD137) genes, which represent activated tumor-specific T-cells." (PMID 33193316, 2020). "There were also more ITGAE (CD103)-expressing and CXCR3-expressing ST2+ Tregs in CRC than in adjacent tumor-free colon." (PMID 31165767, 2019). "For example, ITGAE played an oncogenic role in KICH and KIRC but a tumor-suppressive role in KIRP." (PMID 39436262, 2024). "Complementing the hypothesis that cDC1s migrate in the tumor through the XCL1/2 – XCR1 axis, we show that, besides for NK-cells, XCL1/XCL2 were also expressed by a subpopulation of ENTPD1+ ITGAE+ CD8+ T-cells." (PMID 36741389, 2022). "Furthermore, exhausted clusters specifically expressed tumor-reactive T cell markers (ENTPD1 and ITGAE), while the effect cluster rarely expressed them, indicating that cells belonging to the effect cluster were potentially bystander cells." (PMID 34804045, 2021). "Confirming our previous data, we found that in tumors with M1hot TAMs compared with M1cold TAMs, the tumor-infiltrating CD8+ T cells showed increased expression of genes strongly enriched for TRM signature genes (eg, ITGAE, RBPJ) in addition to cell cycle and cytotoxic/cytokine signature genes." (PMID 32699181, 2020). "DP T cells expressed ITGAE (codes for CD103), and CD69, but not SELL, KLF2, and S1PR1, suggesting a tumor resident phenotype." (PMID 30534127, 2018).
infection (248 papers, 2007 to 2026). The state of being infected such as from the introduction of a foreign agent such as serum, vaccine, antigenic substance or organism. "SA2 infection negatively regulated expression of genes like b-arrestin (ARRB2), integrinAε (ITGAE), hemolytic complement (HC), lymphocyte protein tyrosine kinase (LCK) that are involved in pathogen clearance or induction of immune response." (PMID 25075227, 2014).
cancer (142 papers, 2002 to 2026). A tumor composed of atypical neoplastic, often pleomorphic cells that invade other tissues. "Also, at gene level, an opposite relationship was observed for the same ITGAE gene in different cancer types (e.g., TGCT and LAML)." (PMID 39436262, 2024). "A similar CXCL13+ CD103 (ITGAE)+ CD8+ T cell subtype was previously suggested to play potential roles in mediating B cell recruitment and tertiary lymphoid structure formation in human cancer." (PMID 36423636, 2022).
infectious disease (1 paper, 2023). A disorder directly resulting from the presence and activity of a microbial, viral, or parasitic agent in humans. "Flex-sweep also identified sweep windows in TLR5 (Toll-like receptor 5), ITGAE (integrin subunit alpha E), and APOL1 (apolipoprotein L1), all previously identified as sweeps associated with infectious diseases or pathogen response by both genomic and functional studies." (PMID 37307561, 2023).
ITGAE also shares sentences with these, for which no sentence is quoted: colitis (76 papers); influenza (46); viral infection (40); non-small cell lung carcinoma (24); hairy cell leukemia (21); asthma (20); vitiligo (19); gastric cancer (17); pancreatic cancer (16); cervical carcinoma (13); COVID-19 (11); glioma (11); autoimmune disease (10); bladder cancer (10); head and neck cancer (10); inflammatory bowel disease (10); bacterial infection (9); breast tumors (9); Crohn disease (9); food allergy (9); inflammation (9); lupus (9); atherosclerosis (8); colon carcinoma (8); endometrial cancer (8); head and neck squamous cell carcinoma (8); sarcoidosis (8); Autoimmunity (7); allergic asthma (6); celiac disease (6).
A further 222 diseases each share a sentence with ITGAE in 6 papers or fewer.